IFNGR1 (interferon gamma receptor 1)
Diseases named in the same sentence as IFNGR1 in open-access papers (continued):
Sharing a sentence is not in itself a finding about the gene and the disease.
rectal cancer (4 papers, 2014 to 2025). A primary or metastatic malignant neoplasm that affects the rectum. "It is noteworthy that the single nucleotide polymorphismrs3799488 in IFNGR1 was reported to be associated with increased risk of rectal cancers." (PMID 27286456, 2016). "In particular, the authors demonstrated that the IRF2 mutational status is associated with both colon and rectal cancer, whereas mutations in other genes involved in IFN signaling pathway were uniquely associated with colon (IFN-γ and IRF3) or rectal cancer (IFNGR1, IFNGR2, IRF4, IRF6, and IRF8)." (PMID 28798748, 2017). "A previous study examined genetic variation in IFNG, IFNGR1, IFNGR2 and IRF1-9 with the risk and survival of colon and rectal cancer." (PMID 25350395, 2014). "A genetic polymorphism in IFNGR1 was reported to be associated with increased risk of rectal cancers, however, whether or not this polymorphism reduces IFN-γ receptor function remains to be determined." (PMID 27286456, 2016).
vitiligo (4 papers, 2022 to 2024). Generalized well circumscribed patches of leukoderma that are generally distributed over symmetric body locations and is due to autoimmune destruction of melanocytes. "By performing scRNAseq on vitiligo patient biopsies and experimental vitiligo mouse models with Ifngr1-deficient Pdgfra+ fibroblasts, Xu and colleagues found that fibroblasts activated by IFNγ mediate CD8 T cell recruitment underlying autoimmune depigmentation." (PMID 36591258, 2022). "On the other hand, intradermal injection of wild-type but not Ifngr1 KO-fibroblasts into the tail skin of Ifngr1KO mice resulted in significant local aggregation of CD8+ T cells after the induction of vitiligo." (PMID 35950754, 2022).
AIDS (3 papers, 2012 to 2024). A syndrome resulting from the acquired deficiency of cellular immunity caused by the human immunodeficiency virus (HIV). "There have been no reported cases of non-AIDS, non-immunosuppressive, anti-interferon-γ autoantibodies negative, IFNGR1 gene mutation of TM infection until now." (PMID 37926601, 2024). "Individuals with inherited or acquired defects in TH1 immunity, such as those with IFNγ/IL12B/IFNγR1 polymorphisms or HIV/AIDS, are more susceptible to nontyphoidal Salmonella infections, but not to enteric fever." (PMID 38497655, 2024). "Thus, it would be interesting to compare the sequence of AGM IFNGR1 with other SIV natural hosts in order to evaluate if this might play a role in AIDS resistance." (PMID 22726727, 2012).
chronic hepatitis B (3 papers, 2014 to 2022). "For example, IFN-γ + 874 and IFNGR1 (−56 and −611) have been identified as candidate genetic markers for determining susceptibility to the development of chronic hepatitis B in adults." (PMID 32047575, 2020). "In another study, IFNGR-1 (−56) was suggested as a candidate gene marker for determining susceptibility to the development of chronic hepatitis B." (PMID 32047575, 2020).
chronic periodontitis (3 papers, 2010 to 2018). A chronic inflammatory process that affects the tissues that surround and support the teeth. "Gene coding for the ligand-binding chain of interferon gamma receptor 1, a cytokine that plays a pivotal role in defense against infection, was significantly associated with periodontitis in combination with smoking." (PMID 20170537, 2010). "In combination with smoking, IFNGR1 was significantly associated with periodontitis." (PMID 20170537, 2010).
coccidioidomycosis (3 papers, 2017 to 2023). A fungal infection caused by Coccidioides immitis. "Susceptibility to candidiasis and filamentous fungi has not been described in patients with AR IFNγR1 deficiency; instead, histoplasmosis and coccidioidomycosis were reported in patients with AD partial IFN-γR1 deficiency residing in endemic regions in the United States." (PMID 31572394, 2019).
depression (3 papers, 2019 to 2023). "Carriers of the rare allele of rs9376268 in the interferon-γ receptor 1 (IFNGR1) gene were also shown to have more severe depression." (PMID 35528795, 2022). "Two of these genes, IFNGR1 and AHI1, both linked to ‘abnormal depression-related behavior’, are predicted to have a novel interaction between them." (PMID 31481665, 2019).
eczema herpeticum (3 papers, 2016 to 2022). "Genetic variants in IL-12 and IL-12RB, IFN-γ genes (IFNG) and IFNGR1 leading to partial IFNGR1 deficiency are related to AD in patients susceptible to eczema herpeticum." (PMID 27483258, 2016). "Interestingly, IFNGR1 variants were reported in one study as the most prevalent genetic risk factor for atopic dermatitis complicated by eczema herpeticum (ADEH+)." (PMID 35273610, 2022).
graft versus host disease (3 papers, 2015 to 2023). An immune system disorder that occurs after allogeneic hematopoietic stem cell transplant and is a reaction of donor immune cells against host tissues. "Importance of IFNγ to the immunosuppressive capacity of MSC is highlighted by the fact that MSC from IFNγR1−/− mice are unable to prevent graft versus host disease (GVHD) in contrast to MSC from WT mice." (PMID 26779185, 2015). "Interestingly, wild-type MSCs have been shown to block graft-versus-host disease (GVHD) and delayed-type hypersensitivity in lethally-irradiated recipient mice but not IFNγR1−/− or iNOS−/− MSCs." (PMID 31684035, 2019).
influenza (3 papers, 2013 to 2023). An acute viral infection of the respiratory tract, occurring in isolated cases, in epidemics, or in pandemics; it is caused by serologically different strains of viruses (influenzaviruses) designated A, B, and C, has a 3-day incubation period, and usually lasts for 3 to 10 days. "The interferon signaling pathway was completely attenuated in patients with severe influenza (only one gene was activated: IFNGR1) whereas the pathway was strongly up-regulated in patients with moderate (P = 10−2.8, ratio 0.36, 13 genes) and mild (P = 10−4.8, ratio = 0.33, 12 genes) outcomes." (PMID 25365328, 2014). "Of note, in this study, all influenza-positive children admitted to the PICU, regardless of MODS status, had similar, abundant interferon receptor expression levels (IFNαR1, IFNγR1) at their first time point (data not shown)." (PMID 37533854, 2023).
latent infection (3 papers, 2018 to 2022). "This was in contrast to Tcf7+ cells from latent infection, which maintained relatively higher levels of Gzmm, Ifngr1, and Ccl5." (PMID 35185882, 2022). "In East Africa, a combined linkage and association study of Ugandans has shown that IL10, interferon gamma receptor 1 (IFNGR1), and TNF alpha receptor 1 (TNFR1) variants are linked to active TB, but not with latent infection." (PMID 29868226, 2018).
leprosy (3 papers, 2013 to 2019). Leprosy is a chronic infectious disease affecting primarily the skin and peripheral nervous system. "However, a case report showed that the IFNGR1 polymorphism at position −56T/C was positively associated with an increased susceptibility to leprosy, in Iranian children of the same family." (PMID 23936864, 2013).
mycobacteriosis (3 papers, 2022 to 2025). "Mycobacterial infections occur due to gene mutations that encode the IFNGR1 chain, leading to a loss of cellular responsiveness to type II IFN-γ, which plays a significant role in controlling intracellular bacteria." (PMID 40062101, 2025). "IFNGR1 deficiency is a very rare subtype of MSMD that makes the patient prone to mycobacterial infections and intracellular microorganisms." (PMID 40062101, 2025). "As mutations in STAT1 and IFNGR1 are known to be responsible for both AD and AR forms of mycobacteriosis, the heterozygous variants identified in these genes (STAT1 c.373–2A>C and IFNGR1 c.40G>A/p.(Val14Met) are the most promising causal candidates in this study." (PMID 36338958, 2022).
Sepsis (3 papers, 2017 to 2022). Sepsis is defined as life-threatening organ dysfunction caused by a dysregulated host response to infection. "In the GSE95233 control and sepsis groups, IFNGR1 (interferon gamma receptor 1), and ESAM (endothelial cell selective adhesion molecule) had degree 49 and 21, respectively." (PMID 33667236, 2021). "The main classes of drugs used for the evaluation of sepsis treatment are immunostimulatory drugs (immune targets CSF2RA/B, CSF3R), immunostimulatory cytokines (immune target is IFNGR1/2), and immunosuppressants (PDL1 and CTLA4)." (PMID 36389695, 2022). "We analyzed the immune targets of immune-related drugs to predict their potential use in sepsis and showed that nine target loci (CSF2RA/B, CSF3R, IFNGR1/2, IL7R, PDL1, CTLA4, and LAG3) differed in the high-/low-risk block." (PMID 36389695, 2022).
Splenomegaly (3 papers, 2016 to 2022). Abnormal increased size of the spleen. "For example, we observed that splenomegaly persists in SAVI mice, regardless of which IFN receptor is deleted, and that survival of Ifngr1–/– SAVI mice may be only slightly improved, suggesting additional IFN-independent or combinatorial IFN receptor–dependent effects." (PMID 36073546, 2022).
ZIKV infection (3 papers, 2017 to 2019). "After ZIKV infection, IFN-γ receptor-deficient Tfh cells developed normally, with slight reduction of pre-Tfh cells, and these cells could produce similar levels of IFN-γ, compared with CD45.1+ wild-type Tfh cells in the same chimeras, consistent with that in Ifngr1−/− mice." (PMID 31455769, 2019). "Importantly, all three recombinant viruses were attenuated in Ifngr1−/− mice, demonstrating the critical importance of IFN-γ responses in controlling lethal ZIKV infections, as also reported by other groups." (PMID 28270583, 2017).
anemia (2 papers, 2016 to 2022). A reduction in the number of red blood cells, the amount of hemoglobin, and/or the volume of packed red blood cells. "Indeed, Ifngr1−/−ApcMin/+ mice were found to exhibit more severe anemia." (PMID 27286456, 2016).
asthma (2 papers, 2014 to 2023). "However, the induction of several interferon-related genes (IRF3, IFNAR1, IFNB1, IFNGR1, IL28B) was impaired in patients with asthma." (PMID 24475887, 2014). "Among the genes that were induced in all subjects except for patients with asthma were interferon involved genes (IL28B, IFNAR1), CCL22, and FOSL1 with respect to the upper airways, and several interferon involved genes (IRF3, IFNAR1, IFNB1, IFNGR1, IL28B) in the lower airways." (PMID 24475887, 2014).
atopic dermatitis (2 papers, 2014 to 2022). "The -56C/T promoter polymorphism, where the T allele was associated with higher IFNGR1 transcriptional activity, represented a genetic risk factor for ocular complications of atopic dermatitis." (PMID 25466928, 2014).
combined immunodeficiency (2 papers, 2019 to 2021). A broad classification of inherited disorders presenting at birth that affect both the cell-mediated and humoral aspects of the immune response. "Underlying diagnoses were IL12RB1 deficiency, NFKB1 haploinsufficiency, IFNGR1 deficiency, GATA2 haploinsufficiency, Kabuki syndrome, NEMO deficiency, and undefined combined immunodeficiency (CID)." (PMID 30984189, 2019).
dengue disease (2 papers, 2021 to 2024). Dengue fever (DF), caused by dengue virus, is an arboviral disease characterized by an initial non-specific febrile illness that can sometimes progress to more severe forms manifesting capillary leakage and hemorrhage (dengue hemorrhagic fever, or DHF) and shock (dengue shock syndrome, or DSS). "To investigate how MCs influence maternal antibody-mediated dengue disease, we first generated mice that lacked both MCs and IFN receptors by crossing AG129 (Ifnar1−/− Ifngr1−/−) mice with MC-deficient Sash (KitW-sh/W-sh), and the F1 progeny were then crossed with each other." (PMID 34066286, 2021).
diabetes (2 papers, 2020 to 2023). "Strikingly, we were able to show that diabetes-prone pre-implantation embryos from NOD mice differentially overexpressed some of the previously identified immune-related genes, such as Ifngr1 and Il22ra2." (PMID 32796510, 2020).
Kala-azar (2 papers, 2011 to 2014). "Indeed, results of this study proposed a genetic association between the polymorphism at IFNGR1 and the susceptibility of patients after treatments to PKDL (and not to visceral leishmaniasis)." (PMID 22206035, 2011).
Lymphadenopathy (2 papers, 2022 to 2023). Enlargement (swelling) of a lymph node. "In this article, we described a case with interferon gamma receptor 1 deficiency who came with generalized lymphadenopathy and had systemic aspergillosis." (PMID 37277724, 2023).
mastitis (2 papers, 2018 to 2021). Inflammation of breast tissue during lactation or postpartum due to an obstructed duct or infection. "On the other hand, our qRT-PCR analyses supported the downregulation of PLAUR and IFNGR1 and the upregulation of STC1 and IL19 in the breast milk SC from women with mastitis after treatment with the probiotic." (PMID 30271395, 2018).
metastatic prostate carcinoma (2 papers, 2019 to 2025). A carcinoma that arises from the prostate gland and has spread to other anatomic sites. "For instance, LY96 and IFNGR1 were identified as prognostic genes in thyroid cancer (THCA); LY96 is strongly downregulated in osteosarcoma, where it suppresses cell proliferation, migration, and invasion; and IFNGR1 has been associated with poor prognosis in metastatic prostate cancer." (PMID 41150760, 2025).
mouth ulcers (2 papers, 2019 to 2020). "For example, rs7749390 an intronic variant in the IFNGR1 gene and rs3764613 within PPP5C, showed very strong evidence for associations with mouth ulcers (OR 1.08, 95% CI: 1.07, 1.08; EAF 0.61; P = 2.0e−62 and OR 0.93, 95% CI: 0.92, 0.93; EAF 0.43; P = 7.4e−73, respectively)." (PMID 30837455, 2019).
mycoses (2 papers, 2017 to 2019). "In fact, IL12Rβ1, NEMO, CD40L, and IFNγR1 deficiencies also result in impaired Th17 generation from naïve T-cells which likely contribute to susceptibility to fungal infection." (PMID 31572394, 2019). "F6.1 and F6.2 were the first cases of invasive mycoses reported in AR IFNγR1 deficiency." (PMID 31572394, 2019).
Obesity (2 papers, 2022 to 2023). Accumulation of substantial excess body fat. "The association of the rs13201877 polymorphism of IFNGR1 gene with the risk of obesity development has been well-established in large GWAS." (PMID 36986146, 2023).
osteosarcoma (2 papers, 2020 to 2025). A usually aggressive malignant bone-forming mesenchymal neoplasm, predominantly affecting adolescents and young adults. "Analysis of human (HOS, SaOS-2, 143B) and mouse (LM8) osteosarcoma cell lines by flow cytometry revealed that IFNGR1 was expressed in all cell lines (HOS; 1.92, p = 0.0022, 143B; 1.83, p = 0.011, SaOS-2; 2.14, p = 0.027, and LM8; 1.3, p = 0.0017." (PMID 31914969, 2020).
prostate carcinoma (2 papers, 2019 to 2022). A carcinoma that arises from epithelial cells of the prostate gland. "The enhanced stability of IFNGR1 leads to stimulation of the type II interferon-gamma (IFN-γ) inflammatory reaction pathway in prostate carcinomas." (PMID 35814468, 2022). "This is different from other tumor models, such as in myc-driven prostate cancer, in which EZH2 knockdown restored IFNGR1 expression and further led to activation of IFN-JAK-STAT1 signaling." (PMID 31727135, 2019). "MUC1-C, which could facilitate the expression of IFNGR1 via inhibiting FBXW7 expression, drives dedifferentiation of castrate-resistant prostate cancer (CRPC) cell in a chromatin remodeling-dependent way." (PMID 35814468, 2022).
rheumatoid arthritis (2 papers, 2006 to 2017). A chronic, systemic autoimmune disorder characterized by inflammation in the synovial membranes and articular surfaces. "We therefore investigated the association of those two IFNGR1 single nucleotide polymorphisms with rheumatoid arthritis in a case-control study in a central European population." (PMID 16563189, 2006). "Surprisingly, however, neither position was polymorphic in the 364 individuals examined, indicating that IFNGR1 does not contribute to susceptibility to rheumatoid arthritis, at least in Caucasians." (PMID 16563189, 2006).
Rickettsiosis (2 papers, 2021 to 2025). A group of infectious diseases that is caused by Rickettsia. "We previously reported that Ifnar1−/−; Ifngr1−/− DKO mice, carrying mutations in the genes encoding the receptors for IFN-I (Ifnar1) and IFN-γ (Ifngr1), are susceptible to eschar-associated rickettsiosis." (PMID 39819005, 2025). "Thus, Ifnar1-/-;Ifngr1-/- mice are a tractable model to investigate rickettsiosis, virulence factors, and immunity." (PMID 34423779, 2021).
toxoplasmosis (2 papers, 2012 to 2019). A parasitic disease contracted by the ingestion or fetal transmission of toxoplasma gondii. "To determine if ROP5 deficient (RHΔku80Δrop5) parasites were controlled by an IFN-γ-dependent mechanism, we tested the virulence of ROP5 deficient (RHΔku80Δrop5) parasites in Ifngr1−/− mice, which are unable to respond to IFN-γ and hence, are highly susceptible to toxoplasmosis." (PMID 23144612, 2012).
acute myeloid leukemia (1 paper, 2024). Acute myeloid leukemia (AML) is a group of neoplasms arising from precursor cells committed to the myeloid cell-line differentiation. "In the mouse model of acute myeloid leukemia (AML), IFN-γ receptor 1 (IFNGR1) suppression can decrease the expression of PD-L1 through the MEK/ERK and MYD88/TRAF6 pathways." (PMID 39343796, 2024).
adenoma (1 paper, 2016). A neoplasm arising from the epithelium. "We first determined the transcript levels of Ifngr1 in adenomas and adjacent normal tissues in ApcMin/+ mice by qRT-PCR." (PMID 27286456, 2016).
aspergillosis (1 paper, 2025). Aspergillosis is an infection, growth, or allergic response caused by the Aspergillus fungus. "WES study showed SH2B3 and IFNGR1 mutations, indicating that patients with IFNGR1 deficiency can be presented with aspergillosis." (PMID 40062101, 2025).
Blau syndrome (1 paper, 2025). Blau syndrome (BS) is a rare systemic inflammatory disease characterized by early onset granulomatous arthritis, uveitis and skin rash. "This is supported by a recent case describing a patient with a milder form of Blau syndrome – a monogenic granulomatous disease - due to the interference of a coexisting dominant-negative IFNGR1 mutation." (PMID 40755768, 2025).
breast tumour (1 paper, 2017). "Our study provides evidence that Tualang and Manuka honeys are novel immune potentiators which induce IFN-γ and IFNGR1 expression to potentiate IFN-γ activities in breast tumour cells." (PMID 28479926, 2017).
brucellosis (1 paper, 2019). Brucellosis is a bacterial infection that spreads from animals to people via unpasteurized dairy products or by exposure to contaminated animal products or infected animals. "The purpose of this study was to evaluate the relationship between two single nucleotide polymorphisms (SNPs) at positions -611 and -56 within the promoter region of interferon-gamma receptor-1 gene (IFN- R1) and brucellosis." (PMID 31582997, 2019).
cerebral malaria (1 paper, 2014). A sequestration of Plasmodium falciparum in the brain, which can cause coma and/or seizures. "Genetic variants in IFNGR1 influence susceptibility to mycobacterial infection and cerebral malaria, major infectious diseases which are endemic on the South subcontinent." (PMID 25115870, 2014).
chronic rhinosinusitis (1 paper, 2023). Chronic form of sinusitis. "In this study, we tested the SpA expression in S. aureus from chronic rhinosinusitis patients and investigated the effects of SpA on HNECs inflammation through Interferon Gamma Receptor 1(IFNGR1)/phosphorylated Janus Kinase 2 (p-JAK2) pathway." (PMID 36527461, 2023).
ductal carcinomas (1 paper, 2024). "The immunohistochemical analysis indicated that IFNGR1 protein expression was negative in normal breast tissue as well as in ductal carcinomas." (PMID 39765744, 2024). "IFNGR1 and NFIL3 protein expression levels were negative in normal breast tissue as well as in ductal carcinomas." (PMID 39765744, 2024).